MMP3 (matrix metallopeptidase 3)
Diseases named in the same sentence as MMP3 in open-access papers (continued):
Sharing a sentence is not in itself a finding about the gene and the disease.
cancer (continued). "MMP-1 is thought to be involved in cancer progression and invasion, whereas the mechanism by which MMP-3 contributed was not clarified." (PMID 28446168, 2017). "In B16F10 cancer cells, however, the MMP3 level was found to be consistent regardless of SIRT1 expression." (PMID 26992208, 2016). "Both MMP3 from LC cells and MMP9 from TAM enhance cancer metastasis." (PMID 25961789, 2015). "Among these anti-cancer targets, 3-phosphoinositide-dependent protein kinase-1(PDPK1), MMP1, MMP2, MMP3, nitric oxide synthase (NOS2), and inosine-5′-monophosphate dehydrogenase 2 (IMPDH2) showed similar binding affinity with bruceantin as that of some marketing drugs." (PMID 24429698, 2014). "Moreover, stromelysin-1 or MMP-3 which can degrade ECM and induce cancer invasion and metastasis, showed the decreased expression in fibroblasts." (PMID 20096135, 2010). "Similarly, E-cadherin has been reported to transcriptionally regulate a variety of integrins and matrix metalloproteases (MMP1, MMP2, MMP3, MMP14 and TIMP-1) in other cancer models." (PMID 19257890, 2009). "High levels of MMP13 and its activator MMP3 promote cancer progression rather than T cell response." (PMID 38774209, 2024). "Therefore, we tested whether the M/Ms expressed MMP3 to benefit their activation and affect the integrity of the BBB to facilitate the growth of metastatic cancer cells." (PMID 30616691, 2019). "Besides, WTAP regulates the expression of certain genes related to motility of cancer cells, such as chemokine ligand 2 (CCL2), chemokine ligand 3 (CCL3), matrix metallopeptidase 3 (MMP3), lysyl oxidase-like 1 (LOXL1), hyaluronan synthase 1 (HAS1), and thrombospondin 1 (THBS1)." (PMID 30062093, 2018). "Although significant insights on the role of MMP2, MMP3, and MMP9 in OSCCs and other cancers have been gained, the full functional/mechanistic role of DSPP-MMP20 partnering and interaction in the biology of OSCC and other cancers is just beginning to be explored." (PMID 30002682, 2018). "However, most studies have investigated the relationship between MMP-3 and cancer progression with a focus on cancer cells and not on stromal fibroblasts, which are the major cells expressing MMPs." (PMID 28831065, 2017). "Interestingly, the cancer proliferation effect of MEF-1-conditioned medium was abolished by MMP3 knock-down, but not by AR knock-down (top)." (PMID 26992208, 2016). "Thus EBV-induced MMP3 and MMP9 may work individually or cooperatively to promote cancer progression." (PMID 23409137, 2013). "Based on the broad substrates of MMP3 and MMP9, their potential effects may be involved in multiple steps of cancer progression, including cell survival, proliferation, epithelial-to-mesenchymal transition, migration, angiogenesis, immunosuppression, and metastasis." (PMID 23409137, 2013). "Unfortunately, our study did not yield statistically significant analyses of tested MMP-3 and MMP-10; however, our work focuses only on the early stages of cancer." (PMID 40332487, 2025). "FERMT1, MET, and MMP3 overexpressed in PC tissues, while the expressions of CARD9 were not outstanding in both normal and cancer tissues in PC." (PMID 37727377, 2023). "Unlike its mechanism in cancer metastasis, we show that ENO promotes ECM production and reduces MMP-1 and MMP-3 levels and, thus, ECM degradation." (PMID 34935642, 2021). "Of interest, MMP3 is a druggable target, with a selective inhibitor of MMP3 available (UK370106), but this has not been tested in cancer cells." (PMID 34414229, 2021). "TNF-α has been shown to upregulate MMP-9 gene expression in malignant carcinoma via TNF-R1, and TNF-R1 but not TNF-R2 has been shown to be important in inflammatory responses involving IL-1β and MMP-3 and -9 in murine brain injury." (PMID 19435506, 2009). "Both MMP-3 and MMP-7 in cancer cells may or may not determine tumor resistance to apoptosis." (PMID 38203373, 2023).
cancer (continued). "After adding 740Y-P, PI3K agonist, the expression of SBEM protein in cancer cells of miR-186-5p mimic + 740Y-P group was significantly decreased than the miR-186-5p mimic NC + 740Y-P group, while the protein levels of p-PI3K, p-AKT, MMP1, MMP3 and MMP9 were not significantly changed." (PMID 37477531, 2023). "However, other predicted targets such as SOCS3, PTPRN2, MMP3, PRG1 and BASP1 have not yet been experimentally validated but could be of particular interest on cancer research." (PMID 28346474, 2017). "On the other hands, we found that PCI-64 cells by which MUC5AC was not originally expressed showed no augmentation of MMP-3, α3-integrin or VEGF, indicating that MUC5AC might not play a central role in progression of cancer like PCI-64 cells which have low level expression of MUC5AC." (PMID 20492722, 2010).
infection (54 papers, 2008 to 2025). The state of being infected such as from the introduction of a foreign agent such as serum, vaccine, antigenic substance or organism. "Nevertheless, the loss of COL6A2, MMP1, and MMP3 transcription in WT infection compared to Δvhs infection was considerably greater (8- to 15-fold), thereby confirming their vhs-dependent transcriptional downregulation." (PMID 33148793, 2021). "IL‐17 causes up‐regulation of MMP‐3 gene expression and secretion from epithelial cells exposed to a monocyte‐dependent infection in vitro network." (PMID 29210073, 2018). "We observed decreased expression of several ECM components important for vascular integrity in the dura mater at day 7 post-infection including BM-associated collagens, laminins, and other structural proteins in addition to increased expression of matrix metalloprotease genes mmp3 and mmp9." (PMID 33524035, 2021). "Mmp3 and Cox2 expression were increased in IL‐1β‐treated chondrocytes with Ad‐Zmiz1 infection, compared to the corresponding non‐infected chondrocytes." (PMID 40040621, 2025). "By 24 h post-infection, log-phase Mtb triggered the highest MMP-3 expression, reaching 656.97 pg/mL a three-fold increase compared to both reactivated dormancy phases and 15.9 times higher than uninfected controls." (PMID 41450943, 2025). "At the earliest point, all three infection phases exhibited slightly elevated MMP-3 levels compared to uninfected controls, with statistically significant differences." (PMID 41450943, 2025). "To determine the expression of cellular senescence-related mRNA, we analyzed CDKN2A, CDKN1A, MMP3, and Lamin B1 in the slices 8 d post infection." (PMID 37163429, 2023). "Our results demonstrated that overexpression of activin A via recombinant activin A or Ad‐activin A infection triggered the productions of MMP3, MMP13, and COX‐2." (PMID 36950748, 2023). "MMP-3 levels were significantly increased in the presence of IL-17A (above 100 ng/ml) upon infection with M intracellulare at 1000 MOI at 48 h and 72 h." (PMID 35363832, 2022). "In the case of MMP1 and MMP3, these transcripts were reduced by log2 change of 8 in WT infection, again but these transcripts were only slightly reduced in the HSV1 vhs-GFP infection compared to the mock-infected control at 16 h." (PMID 35758691, 2022). "Neutralization of IL-17A during early (0–2 weeks) infection significantly reduced mortality, bacterial burden, fibrotic lung damage, and lung matrix metalloproteinase (MMP)-3 at 39 weeks postinfection." (PMID 35363832, 2022). "We demonstrated that lncRSPH9-4 helped the infection-caused disruption of the BBB integrity via sponging miR-17-5p, thus promoted the expression of MMP3 and eventually increased the degradation of TJs." (PMID 34198485, 2021). "Here we reported the infection-induced lncRSPH9-4 aggravated disruption of the tight junctions in hBMECs, probably through the miR-17-5p/MMP3 axis." (PMID 34198485, 2021). "The overexpression of mmp3 and mmp7 in infection models indicated a probable role of I10 and EBV in gankyrin-mediated aggressiveness of GC through the upregulation of such kinds of cell migratory genes." (PMID 34585958, 2021). "It has been observed that increased levels of MMPs at diagnosis and higher MMP-3 and 8 at 2 weeks were connected to culture positivity in sputum samples at 2-weeks of infection." (PMID 32218787, 2020). "The mRNA levels of MMP-3, MMP-8, MMP-9, and TIMP-1 were analyzed 12 h after FT explant infection with Ngo strain P9, variant 17 (Pil+Opa+)." (PMID 28932707, 2017). "We next measured pro-inflammatory mediators in splenic tissue by ELISA and observed significant increases in IL-6, CXCL1(KC), IFN-γ, TNF-α, CCL2 (MCP-1), and MMP-3 levels after infection." (PMID 28874800, 2017). "In contrast, the amount of MMP3 transcripts increased upon infection by both viruses and to a higher level in infections by the mutant virus lacking E1A protein production." (PMID 27303733, 2016).
infection (continued). "Using a multiplex assay, we analyzed the protein levels of interleukin (IL)-6, IL-8, monocyte chemotactic protein (MCP)-1 and matrix metalloprotein (MMP)-3 in the supernatant of infected IMR-90 cells at several times post-infection." (PMID 24116215, 2013). "In conclusion, our study demonstrates that elevated levels of MMP-3 and -9 in gastric tissues of mice or cultured cells due to infection by Hp strains (either cag+ve or cag-ve) are inhibited by curcumin treatment." (PMID 21283694, 2011). "In response to P. aeruginosa, genes associated with IFN-γ response to infection (CXCL10, IL-24, IFNγR2) and other mediators of anti-infectious responses (CSF2, MMP1, MMP3, TLR2, S100 calcium-binding proteins A) were markedly up-regulated in wild-type TG cells." (PMID 19399182, 2009). "To do this, we overexpressed Prok2 in primary-culture chondrocytes using Ad-Prok2 infection and evaluated the expression levels of key matrix-degrading enzymes, including MMP3, MMP13, and ADAMTS5, which play pivotal roles in cartilage degradation during OA pathogenesis." (PMID 38057865, 2023). "In addition, expression of MMP-7 or MMP-3 in the liver or small intestine, respectively, increased upon infection, and this was suppressed by anti-TNF-α Ab treatment." (PMID 37939119, 2023). "To determine the relative effect of these additional vhs variants on vhs-induced mRNA degradation, RNA samples were harvested 15 hours after infection and analysed by RT-qPCR for two cellular transcripts we have previously shown to be highly susceptible to vhs degradation—MMP1 and MMP3." (PMID 37343008, 2023). "In vivo, STm infections results in transcriptional upregulation of MMPs family genes, Mmp3, Mmp8, and Mmp28 in PPs and mesenteric lymph nodes (mLNs) 2 days post-infection and further Mmp genes in the inflamed caecum up to 3 weeks post infection." (PMID 35733975, 2022). "Additionally, after 48 hpi the expression of mmp3 was moderately high in infection-I, while in infection-II, -III, and -IV, the expression of these transcripts was similar to that in uninfected control." (PMID 34585958, 2021). "In TC28 cells, MMP3 mRNA level was also increased by Ad-TWIST1 infection by approximately 3 times." (PMID 28220902, 2017). "However, we did observe an increase in MMP3 mRNAs in infection by both wt and the pmE109 mutant viruses." (PMID 27303733, 2016). "Thus, the MAV-1 E1A protein does not measurably affect BBB integrity in the parameters assayed, although it reduces the amount of MMP3 mRNA steady-state expression induced in brains upon infection." (PMID 27303733, 2016). "Collectively, these findings suggest that, in gingiva, the upregulation of MMP12 may be a molecular hallmark of natural aging, while the upregulations of MMP3, MMM9, and IL1B may indicate externally (e.g., infection)-induced aging." (PMID 27391467, 2016). "All these findings suggest that MMP3 may have a role on modulation of NFκB mediated inflammatory response under various condition of infection." (PMID 24416274, 2014). "We then measured the production of IL-6 and MMP-3, one and three days post-infection." (PMID 24116215, 2013). "Specifically, Mmp-3 is transcriptionally upregulated in the hippocampus of infant rats with PM, and its proteolytic activity on the extracellular matrix and its ability to increase soluble Tumor necrose factor alpha (TNF-a) levels are associated with brain injury following infection." (PMID 39469711, 2024). "Future work could aim to identify the relative TIMP/MMP balance within the triple-coculture BBB throughout the infection course, to elucidate the mechanism underlying the reduction in the secretion of MMP-9, but not MMP-3, as a result of infection." (PMID 40295794, 2024). "It was speculated that the elevation of MMP3 in SAA might relate to some infection." (PMID 35571618, 2022).
infection (continued). "However, with the crossover in cytokine and chemokine regulation by MMP2 and MMP3, it remains unclear how the effect of NRTN on the production of MMP2 and MMP3 by macrophages influences the inflammatory response to an infection in vivo." (PMID 33020210, 2020). "Mtb induces the expression of matrix metalloproteinases (MMP-2, MMP-3, and MMP-9) in the placenta, with levels varying by bacterial metabolic state and time post-infection." (PMID 41450943, 2025). "We found that when SDC4 was overexpressed in normal rat chondrocytes by infection of Lv-Sdc4, the expression of COL2A1 and ACAN were decreased significantly, the expression of MMP3 was increased, both in mRNA and protein levels." (PMID 36414669, 2022). "A significant increase in the expression of MMP1, MMP3, MMP9, MMP12, MMP13, and MMP14, was noted in Mtb-AG infected, compared with Mtb-SC-infected rabbit lungs, at both 1 and 4 weeks post infection." (PMID 34732811, 2021). "Using qRT-PCR, these researchers showed that this reduction was vhs dependent based on two sets of genes that exhibited either high (COL6A2, MMP3, and MMP1) or low (GAPDH, ACTB, and RPLP0) reduction in total RNA levels in WT infection." (PMID 33148793, 2021). "Nonetheless, we noticed an increased expression of cell migratory genes mmp3 and mmp7 in infection-III and -IV in comparison to infection-I and -II." (PMID 34585958, 2021). "The hypersensitive MMP1 and MMP3 transcripts underwent slow degradation in CHX-treated cells, but as early as 2 hours after infection this was enhanced during active infection (central panel)." (PMID 30475899, 2018). "The mRNAs for MMP3 and IL1B were also upregulated in young hGFs at 6 h post-infection, compared to 0 h, but these inductions were smaller and delayed compared to those observed in old hGFs." (PMID 27391467, 2016). "In chondrocytes overexpressing ERRγ via infection with Ad-Esrrg, MMP-3 and MMP-13 mRNA levels were dramatically elevated without affecting MMP-12 and ADAMTS5." (PMID 33261216, 2020). "However, we found that the expression of CXCL8, MMP3, and MUC5AC was higher in the MG-infection group compared to the E. coli-infection group." (PMID 31803158, 2019). "We found that overexpression of ERRγ via infection with Ad-Esrrg significantly elevated the mRNA levels and extracellular secreted protein levels of MMP3 and MMP13, without affecting ADAMTS4 or -5." (PMID 29247173, 2017). "Moreover, the MMP3, MMP9 and IL1B levels were more highly stimulated by infection with the oral bacterium, Fusobacterium nucleatum, in old hGFs compared to young hGFs." (PMID 27391467, 2016). "At an earlier time point (24 hours post infection) we found no significant change in B2-m, MMP3, or IL-6 levels." (PMID 25573478, 2015). "We specifically focused on intercellular networks between lymphocytes and airway epithelial cells in TB, and have shown for the first time that lymphocyte‐derived IL‐17 drives both epithelial‐ and fibroblast‐derived MMP‐3 in a TB network, whereas direct infection does not." (PMID 29210073, 2018). "Furthermore, we identified a subset of genes, focused largely around Tnf and matrix metallopeptidase 3 (Mmp3), which were up-regulated in wild-type mice only during r1918 infection and not PR8 infection." (PMID 19461876, 2009). "In addition, serum MMP3 activity was more valuable in diagnosis of NPC than its concentration (0.86 vs. 0.78, AUC), and MMP3 activity can improve the diagnosis of NPC by combining with EBV-infection biomarkers VCA-IgA and EA-IgA with a sensitivity of 91.5% and a specificity of 92.3%." (PMID 32922541, 2020). "We checked MMP3 promoter methylation status by bisulfite sequencing analysis, but the percentage of non-methylated CpG sites did not change after Ad-TWIST1 infection." (PMID 28220902, 2017). "Although there was no substantial difference in absolute MMP-3 and TIMP-1 levels in this patient group, a comparison of median values showed a marked decrease in MMP-3 in patients with prior infection history." (PMID 24412616, 2014).
infection (continued). "A significant (P < 0.05) elevation in serum MMP3 levels was detected in mice with polybacterial infection with or without CIA compared to sham-infected controls and mice with CIA but without polymicrobial infection." (PMID 27405639, 2016).
cardiovascular disease (17 papers, 2013 to 2025). "MMP3 is considered to be a potential marker to predict long-term risk of cardiovascular diseases." (PMID 32330120, 2020). "Emergence of IL-1 as a target in cardiovascular disease prompted the investigation of the redundancy of IL-1α and IL-1β in the induction of MMP-3 and other matrix-remodeling enzymes in human cells." (PMID 27032103, 2016). "Some peripheral cytokines frequently studied in cardiovascular disease such as matrix metalloproteinase-1 (MMP-1), matrix metalloproteinase-3 (MMP-3), osteopontin, and pentraxin-3 can be used as markers to reflect vascular inflammation, endothelial function, or permeability of the BBB." (PMID 38581060, 2024).